CD4 (CD4 molecule)
Diseases named in the same sentence as CD4 in open-access papers (continued):
Sharing a sentence is not in itself a finding about the gene and the disease.
AIDS (continued). "Other predictors of non‐AIDS death in the fully adjusted model included being employed, age> 40 years old, history of injection drug use and CD4 count above 500 cells/μL." (PMID 32437092, 2020). "In the field of HIV, 95% quiescent lymphoid CD4+T cells died of caspase-1-mediated pyroptosis triggered by abortive viral infection and blocking CD4+T cell pyroptosis was considered a potential “anti-AIDS” therapy." (PMID 32258157, 2020). "Slan+ monocytes accumulate in viremic people as well as in cART virosuppressed people who have experienced low CD4 count nadirs, but they are depleted during AIDS." (PMID 32903610, 2020). "Regarding HIV-related variables, 616 (72.9%) were men who had sex with men (MSM), and 80 (9.4%) had prior AIDS-defining conditions, with a median CD4 + cell count of 574 cells/mL (413–787 cells/mL), and 410 (48.5%) with detectable HIV viral load." (PMID 33716992, 2020). "Among PyVs and hepatitis viruses tested, BKPyV and HBV DNA positivities among HIV/AIDS patients with CD4 + counts < 200 cells/mm3 were significantly higher than those with CD4 + counts > 500 cells/mm3 (P = 0.045 for HBV; P = 0.002 for BKPyV)." (PMID 33051567, 2020). "The lymphocyte number, CD3+ T cell number, CD4+ T cell number, CD8+ T cell number, and CD4+/CD8+ T cell ratio of the AIDS-related PCP patients are significantly lower than those of HIV/AIDS without PCP (P <0.01)." (PMID 32911508, 2020). "For example, in AIDS clinical trials, CD4 count is the most important clinical measurement that indicates disease progression among HIV/AIDS patients earlier than disease or death." (PMID 32953683, 2020). "We found that compared with people who have AIDS (CD4 cells < 200 cells/mm3), people who have a normal range of CD4 cells (≥ 500 cells/mm3) have $1046 less in expenditures on average." (PMID 32197598, 2020). "In this study, immunohistochemical methods were used to detect PD-1 in the intestinal mucosa of patients with HIV/AIDS; CD4+ T cells were also enumerated." (PMID 32891157, 2020). "The findings of this meta-analysis showed that HIV/AIDS patients with CD4+ T-cell count <200cells/μl were statistically significant as compared to their counterparts (AOR: 3.53, (95%CI: 1.98, 6.27))." (PMID 33382867, 2020). "The latest CD4+ T cell count and CD4+:CD8+ T cell ratio were both individually strongly associated with the development of a new AIDS events on cART." (PMID 32664736, 2020). "Infected individuals are assumed to experience progressive decline in CD4+ T-cell counts and proceed through the five stages before they are diagnosed with AIDS." (PMID 31964392, 2020). "When the NFATP was first established, the indication for ART initiation was a CD4+ T cell count less than 200 cells/mm3 or advanced AIDS status." (PMID 31939111, 2020). "Various studies have defined HIV/AIDS progression based on CD4+ T-cell counts and employed Markov process models to estimate HIV incidence." (PMID 31964392, 2020). "The fitted results show that both models can describe the trend of the epidemic well, including the number of annual HIV/AIDS diagnosis and annual HIV cases linked with CD4 counts in each stage." (PMID 32532238, 2020). "Previous studies have indicated that opportunistic infection in HIV/AIDS patients is strongly correlated with CD4+ T cell count." (PMID 32911508, 2020). "As we mentioned, the time of the onset of AIDS symptoms, due to gradual CD4 T cell depletion, varies broadly among untreated individuals." (PMID 33142907, 2020). "Two-stage modeling and joint model (JM) approaches were used to evaluate the association between CD4 (or CD4/CD8 ratio) slope within two years since ART initiation and a composite endpoint (AIDS, serious non-AIDS events and death) after two years of ART." (PMID 31905222, 2020). "The steady decline seen in the CD4+ T cell population is not well understood but is the result that leads to the progression of AIDS." (PMID 32824563, 2020).
AIDS (continued). "Historically, ART was initiated in patients with a CD4 count of below 350 or those diagnosed with an AIDS-defining illness." (PMID 33141357, 2020). "Twenty-seven studies (44%) excluded PLWH taking antibiotic prophylaxis, and 11 (18%) contained stipulations related to active opportunistic infections or history of AIDS-defining conditions (excluding malignant neoplasm and CD4 count)." (PMID 33258905, 2020). "In the context of the HIV and AIDS pandemic, the enumeration of CD4 antigen-positive T cells is used to determine the immune status of patients with immune deficiencies such as HIV/AIDS or suspected of becoming so." (PMID 32799909, 2020). "In 1993, the CDC expanded its definition of AIDS to include all HIV positive people with CD4+ T cell counts below 200 per microL of blood or 14% of the total lymphocytes." (PMID 32953363, 2020). "This study provides an insight into the associations of CD4+ T cell count and CD4+:CD8+ T cell ratio with ratio normalization and the development of a new AIDS event among PWH who achieved viral suppression on cART." (PMID 32664736, 2020). "As a defined approach to understand the disease, HIV/AIDS prospective cohort studies have in conjunction with the CD4+ count routinely gathered more information from different clinical platforms during the patient follow-up care." (PMID 32190387, 2020). "Our narrative analysis showed that male sex, cigarette smoking, family history of alcohol use, missing ART medication, mental distress, khat chewing, low CD4 count, and low income were among the associated factors for AUD in people with HIV AIDS." (PMID 32831129, 2020). "In this study only 13.2% of KPs had a CD4 of <200 cells/mm3 at initiation of ART further explaining the low prevalence of AIDS-defining malignancies including Kaposi sarcoma." (PMID 32614906, 2020). "Late presentation (LP), defined as a CD4 count < 350/mm3 or an AIDS-event at HIV-diagnosis, remains a significant problem across Europe." (PMID 33028235, 2020). "Even in the patients with CD4 T cell counts below 200 cells per ml (therefore fulfilling the definition of AIDS), 3 of 6 had positive induration of ≥ 5 mm in response to DPPD." (PMID 32737693, 2020). "HIV infection results in chronic activation of T cells, promoting activation-induced CD4+ T-cell death, resulting in lower CD4+ T-cell counts and progression to AIDS." (PMID 32369533, 2020). "HIV is known to gradually deplete native and memory CD4+ T cells and ultimately result in acquired immunodeficiency syndrome (AIDS)." (PMID 33172001, 2020). "Human immunodeficiency virus (HIV-1) infection is characterized by high viral replication and a decrease in CD4+ T cells (CD4+TC), resulting in AIDS, which can lead to death." (PMID 32711474, 2020). "The association between CD4+ T-cell counts <200cells/μl and intestinal parasitic infection among HIV/AIDS patients was computed using six studies." (PMID 33382867, 2020). "This study aimed to evaluate the baseline characteristics of PLWHA aged ≥ 50years at recruitment to HIV/AIDS clinic compared against the viral load (VL) and CD4 count among patients attending Kisii Teaching and Referral Hospital (KTRH), Kenya." (PMID 34394214, 2020). "Nine out of the 11 COVID-19/AIDS patients had relatively high CD4 count (>200/μl) and undetectable HIV viral load (20 copies/ml)." (PMID 32818208, 2020). "Before the widespread use of ART, the median CD4 count for patients with OC was 101 (29 to 280) cells/mm3 in a Ugandan prospective study and the median survival time was 3.1 months in the untreated AIDS patients." (PMID 32982560, 2020). "The effect is reproduced experimentally in nonhuman primates where infection with chimeric simian/human immunodeficiency viruses leads to rapid CD4 T cell depletion, AIDS, and death within 1–2 years." (PMID 33142907, 2020).
AIDS (continued). "Nine out of the 11 COVID-19/AIDS patients had relatively high CD4+ T lymphocyte count (>200/μl) and undetectable HIV viral load (20 copies/ml), and ten of them were on antiretroviral therapy." (PMID 32818208, 2020). "For example, women in the older age group tended to be followed up in more recent calendar years, generally had higher CD4+ T-cell counts, were more likely to have had a prior AIDS event, and were more likely to be on cART and to have a suppressed VL." (PMID 33287689, 2020). "The primary outcomes were CD4 cell count and self-reported adherence measured with the AIDS Clinical Trial Group (ACTG) questionnaire." (PMID 33228562, 2020). "We found that compared with people who have AIDS (CD4 cells < 200 cells/mm3), people who have a normal range of CD4 cells (≥ 500 cells/mm3) have $1046 less in expenditures on average (column 2)." (PMID 32197598, 2020). "These methods were initially developed using AIDS diagnosis data only, but were later extended to use both HIV and AIDS diagnoses, and then to further account for CD4+ T-cell counts at diagnosis." (PMID 31964392, 2020). "Mangal evaluated the effects of regional and age-specific differences on mortality and CD4+ cell progression of HIV/AIDS, using a hidden Markov model." (PMID 32228523, 2020). "In 2014, the standard of free antiviral treatment for AIDS in China was adjusted from 350 to 500 CD4-cells/μL." (PMID 33143744, 2020). "Though common in pre HAART era with an incidence of 26-46%, it is still occurring to date in AIDS patients with CD4 <100 and in presence of opportunistic infections or when they develop resistance to the first line ART drugs." (PMID 32429962, 2020). "Hazard of AIDS increased about 83% for CD4 levels < 350 compared to CD4 levels≥ 500 (P-value = .018)." (PMID 31996148, 2020). "The decline of IFN-γ-producing CD4+ T cells in AIDS is a major contributing factor in reactivation of quiescent Toxoplasma gondii to an actively replicating stage of infection." (PMID 32753607, 2020). "Blood samples with low concentration CD4 cells that mimic blood from HIV/AIDS patients were made by diluting blood with phosphate buffered solution." (PMID 32630535, 2020). "In this study, we also demonstrated that, in cART-naive AIDS patients, one or more serious NADEs were prone to co-occur among some patients with age ≥ 50 years and/or CD4 ≤ 350 cells/ul." (PMID 33351812, 2020). "INRs have a highly activated and exhausted CD4+ and CD8+ T-cell profile, which increases their risk of an AIDS related comorbidity." (PMID 33071649, 2020). "Further evidence has demonstrated that low CD4+/CD8+ ratios among PLWH are associated with neurocognitive disorders, lung cancer, pulmonary emphysema, and AIDS-related mortality." (PMID 32487185, 2020). "Most patients with late presentation, advanced HIV disease, or ADE have relatively low CD4+ cell count or develop AIDS symptoms." (PMID 32680536, 2020). "The progression of the disease due to the continuous activation of the immune system and the low levels of CD4+ T cells can lead to the development of the acquired immunodeficiency syndrome (AIDS)." (PMID 32765522, 2020). "Following ART withdrawal, all control animals showed viral rebound after 3, 9, 11 or 120 weeks, with 2 animals (T511 and T508) progressing rapidly to AIDS, with pulmonary signs and CD4+ T cell depletion within a few weeks of the onset of post-ART viremia." (PMID 32130229, 2020). "The older group of patients in our cohort presented with lower CD4 counts and a higher incidence of AIDS defining conditions compared to the younger group." (PMID 33129258, 2020). "The majority of participants (n = 34; 65%) had a documented history of AIDS, defined by a CD4 nadir count of <200 cells/μl and/or a history of opportunistic infections." (PMID 32024712, 2020). "Patients with an AIDS defining illness or a CD4 count <200 cell/μL were started with a combination of ART." (PMID 32442166, 2020).
AIDS (continued). "Over two-thirds of the older patients with a new diagnosis of HIV presented with a CD4 count < 200, or an AIDS-defining illness." (PMID 33129258, 2020). "HIV selectively infects CD4+ T cells and macrophages and depletes CD4+ T cells, which in fact is coincident with the onset of AIDS symptoms." (PMID 33142907, 2020). "Neurotoxoplasmosis usually occurs in advanced cases of AIDS, when the CD4+ count is less than 200 cells/mm3." (PMID 32953363, 2020). "CD4+ T cell count and CD4+:CD8+ T cell ratio are both individually associated with ratio normalization and the development of new AIDS events after cART." (PMID 32664736, 2020). "In the present study, the CD4+ T cell counts of the AIDS-PCP patients were less than 200 ×106/L, and most were lower than 100 ×106/L." (PMID 32911508, 2020). "Among patients with HIV/AIDS, the risk of CMV infection increases in association with diminished CD4+ T-cell counts." (PMID 32891157, 2020). "These machines are widely distributed in Sub Saharan Africa by the PEPFAR (The United States President ́s Emergency Plan for AIDS relief) program for CD4 counts." (PMID 32374771, 2020). "Note that the limited-division model above predicts an abrupt drop in CD4 T cell count before the onset of AIDS, instead of the gradual decline usually observed in patients." (PMID 33142907, 2020). "Those with CD4+ T‐cell count < 200 cells/μL: HR: 7.74 (vs. above 500 cells/μL); 95% CI: 5.91 to 10.13; p < 0.001) had the highest hazard of AIDS‐related death." (PMID 32437092, 2020). "HIV/AIDS patients with CD4 cell count <200 cells/mm3 were two times more likely under nourished than patients with CD4 cell count ≥200 cells/mm3 (AOR = 1.85, 95% CI, 1.38–2.47)." (PMID 32163485, 2020). "Our results indicated that the burden of CKD was 2.1% among cART-naive AIDS patients in China, which increased with age and mainly occurred in patients with CD4 ≤ 350 cells/ul." (PMID 33351812, 2020). "In 2018, the President’s Emergency Plan for AIDS Relief announced that they will reduce their overall level of support in donor countries for CD4 testing to prioritize viral load testing." (PMID 30892272, 2019). "Cryptococcus infection is considered to be an indicator of advanced AIDS stage, which is characterized by a low CD4 cell count." (PMID 32082071, 2019). "In those with a low postseroconversion level of CD4 cells, progression to AIDS is faster (and the time to AIDS shorter) than among those with a higher postseroconversion level of CD4 cells." (PMID 30622192, 2019). "After adjusting for demographics, comorbidities, AIDS status, CD4+ count, and viral load, HAART was found to be significantly associated with a higher risk of incident OIs, except toxoplasma encephalitis." (PMID 30837537, 2019). "bieneusi in this study was interpreted by administration of ART treatment in all patients and use sulfamethoxazole-trimethoprim treatment during the course of AIDS for patients with CD4 T-cell count less than 200 cells/μl." (PMID 31110984, 2019). "The mean duration of time since the diagnosis of HIV/AIDS was 2.7 ± 1.21 with a mean CD4 count of 692 ± 102.4 cells/m3." (PMID 30783537, 2019). "Secondly, the DRG database has very limited clinical information, which would have been important to better understand the clinical profile of HIV/AIDS patients (e.g. the number of years the patient is engaged in care, viral load, CD4 cell count, ART regime)." (PMID 31077218, 2019). "Five patients had HIV/AIDS (16.1%), 4 of them with CD4 counts below 200 cells per mm3 at PML diagnosis and 1 of them after developing immune reconstitution syndrome 5 months after starting antiretroviral therapy at CD4 count 384 cells per mm3." (PMID 30815501, 2019). "In fact, only ≈30% of T. gondii seropositive AIDS patients will develop a reactivated TE, even if the CD4+ T cell count is very low." (PMID 30873157, 2019).
AIDS (continued). "Since 2011, the World Health Organization recommends CrAg screening for people living with HIV/AIDS (PLHAs) with CD4 counts <100–200 cells/μl." (PMID 31344140, 2019). "We aim to contribute to these efforts by focusing on improving the situation in developing countries and ultimately promoting human health by developing a portable CD4 cell analyzer for monitoring the effectiveness of the ART for patients with HIV/AIDS." (PMID 30875995, 2019). "In the Women’s Interagency HIV Study (WIHS) and Multicenter AIDS Cohort Study (MACS), a current CD4+ T-cell count < 200 cells/mm3 was linked to carotid plaque (defined as a carotid IMT 1.5 mm)." (PMID 31429736, 2019). "Firstly, this work is a retrospective study that included three groups of patients (defined by changes in CD4 T-cell counts and AIDS disease progression rates) with substantial differences in demographic and clinical characteristics." (PMID 30841566, 2019). "The study was conducted to assess the pattern of malaria parasite density at different levels of CD4 T-cells among people living with HIV/AIDS in Western part of Kenya." (PMID 31354844, 2019). "HIV infection results in a gradual depletion of CD4 T‐lymphocytes, eventually compromising the host immune system and ultimately resulting in acquired immunodeficiency syndrome (AIDS)." (PMID 31641451, 2019). "These infections are typical of advanced AIDS despite the fact that these patients had essentially normal numbers of CD4+ T cells and other lymphocytes." (PMID 31572394, 2019). "At the start of IMAT in October 2015, Tanzanian National Guidelines for the Management of HIV and AIDS stated that even for key populations, treatment should be initiated for CD4 < 350 cells/μl." (PMID 30823440, 2019). "It was reported that AIDS patients whose CD4 + T cells counting was less than 50 per mm3 blood were most likely to experience persistent diarrhea, weight loss, and abdominal pain associated with E. bieneusi or E. intestinalis infections." (PMID 30816168, 2019). "A higher proportion of the patients starting TDF/FTC+DTG, TDF/FTC+bDRV and TDF/FTC+RAL had a CD4 cell count below 200 cells/μL and an AIDS diagnosis at start of treatment." (PMID 31449566, 2019). "The possible reason that cryptococcal meningitis was a leading cause of death is because of the fact that, majority of patients admitted with AIDS-related illnesses had a CD4 cell count of <200 cells/μL." (PMID 31887156, 2019). "Disease-related factors associated with HRQoL included stage and time since diagnosis, current CD4 count/viral load, and severity of HIV/AIDS-related symptoms, and being on ART was associated with better physical and mental health." (PMID 30606187, 2019). "Morbidity/mortality due to non-AIDS events, which are properly predicted by the CD4/CD8 ratio and VACS index, have become particularly remarkable in HIV-infected patients receiving effective combined antiretroviral therapy (cART)." (PMID 30818365, 2019). "VL disease while on ART and low CD4 count is a WHO AIDS-defining illness and an indicator of advanced HIV disease and possibly undiagnosed ART failure." (PMID 30789910, 2019). "Lower CD4+ cell counts have been associated with opportunistic infections such as tuberculosis and PJP among HIV/AIDS patients." (PMID 31851879, 2019). "Additional testing confirmed the diagnosis of HIV/AIDS with a CD4 count of 52 cells/mm3, complicated by disseminated histoplasmosis." (PMID 31214373, 2019). "This shows that progression of HIV/AIDS for patients on treatment is better explained by the changes in the viral load levels than the changes in the CD4 cell count levels." (PMID 30770728, 2019). "T. gondii seropositive AIDS patients, with low CD4+ T cell count (<200/μl) and with specific antibodies against T. gondii proving prior infection, are at risk of developing a reactivated TE due to the loss of T cell-mediated control of persisting brain cysts." (PMID 30873157, 2019).